APOE (apolipoprotein E)
Diseases named in the same sentence as APOE in open-access papers (continued):
Sharing a sentence is not in itself a finding about the gene and the disease.
dementia (continued). "Moreover, individuals with higher dementia risk associated with APOE exhibit an elevated N6FA/N3FA ratio in the brain." (PMID 40695676, 2025). "In both samples, hypothesis two was supported, with consistent patterns across both cohorts indicating that greater social adversity increased the risk of dementia in all the APOE allele groups." (PMID 41264567, 2025). "Notably, extensive population-based studies have consistently reported lower plasma ApoE levels in individuals carrying one or two ε4 alleles, and have linked these reduced levels to an increased risk of dementia and mortality, independently of genotype." (PMID 40671162, 2025). "We additionally assessed sex differences stratified by APOE ε4 carrier status excluding carriers of the ε2 allele, given that the possession of this allele confers some protection against cognitive decline and dementia risk." (PMID 40329777, 2025). "Moreover, adding APOE ε4 genotype to the risk score improved the prediction power of the CAIDE dementia risk score in our study, and a similar finding has been shown earlier in a clinical sample." (PMID 39863319, 2025). "This large population-based cohort study found that the association between CMP and dementia may be modified by APOE ɛ4 genotype." (PMID 40101131, 2025). "After adjusting for BMI, waist circumference, homeostatic model assessment for insulin resistance (HOMA-IR), hypertension, lipid levels, and APOE ε4 status, individuals in the highest sex-specific tertile of leptin had a lower risk of developing dementia and AD." (PMID 41516046, 2025). "This prospective cohort study, included 415 072 participants from UK Biobank, found that CMP was associated with a higher risk of dementia, and this association may be modified by the APOE genotype." (PMID 40101131, 2025). "CVD and dementia may share common genetic factors, including mutations in the presenilin and apolipoprotein E (ApoE) genes." (PMID 40867851, 2025). "Therefore, the APOE alleles will have more room for their phenotypical expression, making evident its harmful or beneficial impact on dementia risk." (PMID 41264567, 2025). "The intriguing observations of an association of hearing loss with dementia in APOE ε4 carriers suggest that targeting assessment and correction of hearing loss to this at-risk subgroup may be particularly cost-effective." (PMID 41191359, 2025). "This was shown in the follow-up regression analyses in the present study, where expression of the CRF-AD pattern was significantly negatively associated with global WMH volume while accounting for age, sex, and cardiovascular and dementia risk factors (i.e., vascular risk level, APOE status)." (PMID 40641621, 2025). "We evaluated whether including objective hearing loss as a risk factor improved the estimative accuracy of a dementia prediction model based on age, sex, and APOE ε4 genotype and found that it did." (PMID 41191359, 2025). "The ε 4 genotype of ApoE protein regulates α-Syn pathology in humans and is linked to a heightened risk of dementia among patients with PD, while ApoE ε 2 may prevent the aggregation of α-syn and its link with neurodegenerative processes in synucleinopathies." (PMID 40933823, 2025). "This was done to try to discover if all of the effect of APOE variation (here, possession of one or two e4 alleles) on individual differences in apparently healthy cognitive ageing was due to preclinical dementia; this has been referred to as the “prodromal effect”." (PMID 40386430, 2025). "This association was strongest in younger individuals and in APOE-ε4 carriers which emphasizes the importance of early intervention as well as in those with higher dementia risk, as they may benefit more." (PMID 40551205, 2025).
dementia (continued). "In the United States, dementia affects 6 million Americans and contributes to more than 100,000 deaths per year, and an estimated lifetime risk of acquiring dementia is 42% with higher risk in women, the African American population, and APOE e4 carriers, ranging from 45% to 60%." (PMID 41156633, 2025). "The association between dream recall and a strong genetic risk factor for AD (APOE ε4), as well as between dream recall and cognitive decline, dementia and an AD biomarker (p-tau217), can be considered a Mendelian randomization test corroborating the relationship between dream recall and AD." (PMID 41001478, 2025). "These may include factors already associated with cognitive dysfunction and dementia in other populations, such as apolipoprotein E, complement receptor 1, clusterin, sortilin-related receptor 1, catechol-O-methyltransferase and BDNF." (PMID 40235626, 2025). "However, a case–control GWAS (with family history of dementia as exclusion criteria in cases) with 9 of 13 significant SNPs in the APOE region implicated APOE, APOC1, TOMM40, and NECTIN2 in the prediction of clinical diagnosis of AD in the Chinese population." (PMID 40352683, 2025). "Additionally, dementia risk factors such as T2D, or genetic risk such as the APOE-ε4 allele were also reflected in the design of MET-FINGER, IRMCI and PENSA RCTs." (PMID 41145344, 2025). "Compared with APOE‐ε4 negativity, both APOE‐ε4 heterozygosity (β = 10.498, T = 2.608, p = 0.00931) and APOE‐ε4 homozygosity (β = 17.283, T = 2.316, p = 0.02086) were associated with steeper decline in CSF Aβ1‐42 on approach of age of parental dementia onset." (PMID 40018326, 2025). "The ApoE3-Ch mutation strongly protects against early-onset AD, as evidenced by a homozygous index patient who developed only mild dementia much later in life than expected, highlighting the importance of studying rare ApoE variants in AD pathogenesis and protection." (PMID 39944166, 2025). "This is consistent with another study, which found that participants with any APOE-ε4 allele had 2.42 times higher odds of developing dementia in European ancestry samples and 1.77 times higher odds in African ancestry samples compared to those without the allele." (PMID 41264616, 2025). "In terms of genetic biomarkers, it has already been reported that apolipoprotein E (ApoE) ε4 allele is associated with higher AD risk than the more common ApoE ε3 allele, highlighting the importance of genetic testing in dementia assessment." (PMID 40099249, 2025). "Additionally, we observed an interaction between PUFAs and APOE genotypes on dementia incidence, dementia mortality, and all-cause mortality." (PMID 40695676, 2025). "Notably, high APOE genetic risk was found to attenuate the protective effects of eBMD on dementia, aligning with findings regarding the impact of APOE-ε4 carrier status on DXA-BMD." (PMID 40668308, 2025). "Recently, the European Medicines Agency (EMA) approved marketing authorization for Lecanemab in patients with mild cognitive impairment and mild dementia due to AD, except for APOE-ε4 homozygotes due to increased risk of Amyloid Related Imaging Abnormalities (ARIA)." (PMID 40000321, 2025). "Genetic risk factors, such as the ε4‐allele of apolipoprotein E, may also modulate the influence of social determinants on dementia risk, underscoring the need for further research." (PMID 40717690, 2025). "The present study aimed to establish whether possession of an APOE e4 genetic risk variant for dementia is associated with impaired perceptual discrimination in mid‐life." (PMID 40492513, 2025). "Finally, lower neighborhood social cohesion was associated with increased dementia risk, but only among APOE-ε3ε3 carriers." (PMID 41264567, 2025). "Future studies are needed to confirm whether physical activity levels during certain periods of the adult life course confer differential dementia risk reduction by APOE ε4 status." (PMID 41259024, 2025).
dementia (continued). "The most common type of dementia, AD, is considered a polygenic disease, as the presence of multiple polymorphisms in specific proteins, such as the apolipoprotein E (ApoE), might increase the likelihood of developing the disease and, thus, dementia." (PMID 39940679, 2025). "Whether lifestyle‐based dementia risk in midlife impacts risk of incident cognitive impairment (ICI) in the presence of apolipoprotein E (APOE) ε4 allele or plasma pTau217 remains unknown." (PMID 40799136, 2025). "While α-synuclein and amyloid/tau biomarkers have not been validated in ADHD populations, studies in neurodegenerative disorders indicate that GBA gene mutations and APOE-ε4, particularly in carriers, are associated with accelerated cognitive decline and dementia onset." (PMID 41477452, 2025). "One possibility is that genetic factors, such as the apolipoprotein E (APOE) ε4 allele, and family history of dementia (FH), both of which have been identified as important determinants of AD risk, may play a role." (PMID 39822299, 2025). "Controversies exist regarding whether APOE is a risk for stroke, in which the effect might be different depending on the stroke subtype or the presence of dementia." (PMID 39621511, 2025). "Additionally, APOE ε4, a risk gene for various dementia-related diseases, along with P/LP Variants, constitutes the genetic foundation of dementia." (PMID 40427062, 2025). "To address this, we reanalyzed the association between APOE and dementia status using different age cut-offs in the control group (e.g., >49yrs, >59yrs, >69yrs, >79yrs) and showed that, even for proxy cases, the older control groups numerically increased the AGRs." (PMID 40568661, 2025). "Chronic musculoskeletal pain (CMP) is associated with the risk of dementia, yet little is known about whether this association is modified by APOE genotype and whether analgesics may mitigate the risk effect of CMP on dementia." (PMID 40101131, 2025). "Multidomain lifestyle interventions, e.g., based on the Finnish Geriatric Intervention Study to Prevent Cognitive Impairment and Disability (FINGER), reported promising cognitive benefits in older individuals at risk of dementia including in those with genetic susceptibility (APOE-ε4 carriers)." (PMID 41145344, 2025). "Moreover, it resulted in reduced statistical power to further explore subgroup-specific associations, including by age, for example, to examine risk of young-onset dementia, sex and ApoE status or genetic predisposition to dementia." (PMID 41341656, 2025). "Since non-APOE genetic factors are also important contributors to dementia risk, investigating potential effect modification by PRS provides further insights into whether multimorbidity impacts brain health differently across genetic risk profiles." (PMID 40425445, 2025). "Moreover, interactions of AGEs with APOE ε4, the most important genetic risk factor for dementia at older age, have been suggested." (PMID 38218902, 2024). "Previous research data suggest that apolipoprotein E (APOE) may be the primary candidate gene among those shared by dementia and mortality, as it is strongly associated with incident dementia and increased mortality." (PMID 38078564, 2024). "However, T allele carriers in the MAPT rs2471738 polymorphism were more represented among patients with dementia and apolipoprotein E (APOE) ɛ4 carriers." (PMID 39386049, 2024). "HSV-1 infection has been linked to increased risk of dementia, particularly among APOE ε4 carriers, and in vitro studies suggest that VZV reactivation and neuroinflammation could induce reactivation of HSV-1, leading to AD-related changes." (PMID 39138535, 2024). "While some studies suggest that the ε4 allele may be the main cause of sleep disruption in elderly individuals at risk of dementia, others emphasize that sleep deprivation and APOE genotype may only amplify each other's adverse effects." (PMID 38421124, 2024).
dementia (continued). "Affective disorders are also associated with an increased risk of dementia, and as lower ApoE levels may be associated with dementia, we expected that the affected twins would have decreased ApoE levels." (PMID 38673634, 2024). "Also in males, AA genotype with one APOE e4 was associated with increased risks of all-cause dementia (1.27, 1.04-1.55), AD (1.45, 1.09-1.94) and other types dementia (1.40, 1.08-1.81)." (PMID 38863509, 2024). "Literature on vitamin D and homocysteine in relation to the APOE genotype is limited, but a pattern similar to that of n‐3 PUFAs has been demonstrated for other preventive strategies to lower dementia risk, with APOE ε4 carriers benefitting more in preclinical stages." (PMID 38865433, 2024). "On the other hand, there might be a possible synergistic effect of the MBI psychosis domain and APOE e4 allele on the risk of dementia, although future studies are needed to replicate these results." (PMID 38473892, 2024). "The aim of this study was to investigate the roles of HSV, HSV-1 specifically, and CMV in AD and dementia risk, including examination of potential interactions with APOE ɛ4 carriership and the effects of anti-herpesvirus treatment, in a prospective cohort of same-age individuals." (PMID 38306033, 2024). "Diabetes increases dementia risk by up to 35% in a vulnerable population with ApoE ε4 allele." (PMID 39064140, 2024). "Moreover, diabetes was considered a strong risk factor for early-onset dementia (age < 65 years), with an HR (95% CI) of 1.65 (1.15–2.36) even after adjusting for apolipoprotein E status, one of the major genetic risk factors in early-onset dementia." (PMID 39124653, 2024). "With the current increase in interest in commercially available APOE-genetic screening tests, like 23andMe, and associated requests to explain genetic results, and growing demand of personalised dementia risk reduction, the need for accurate education about genetic risk and disclosure impact arises." (PMID 38167083, 2024). "The APOE ε4 allele is the most established genetic risk factor for sAD38 and may also play a role in the risk and age at onset of dementia in DS39." (PMID 38553642, 2024). "This again emphasises the strength of APOE in dementia risk prediction." (PMID 39160600, 2024). "apoE has also been implicated in several metabolic abnormalities, including abnormal glucose metabolism, altered lipidome and metabolome, mitochondrial dysfunction, and decreased oxygen consumption, all of which are involved in the pathology of dementias." (PMID 39031528, 2024). "Subsequently, we tested for interactions to investigate whether sex and APOE ε4 carrier status modified the association between the nutrient status index and dementia incidence." (PMID 38865433, 2024). "Meanwhile, out-of-insurance testing or direct-to-consumer (DTC) testing of the APOE genotype has been available, especially for those who are cognitively normal but are worried about their risk of dementia to prepare in advance before developing dementia." (PMID 38225507, 2024). "In addition, the APOE e4/e4 genotype is strongly associated with dementia risk in all specifications." (PMID 38807092, 2024). "For example, apolipoprotein E (APOE) genotypes—the strongest genetic risk (for APOE ε4 carriers) and protective (for APOE ε2 carriers) factors for late‐onset dementia—are suggested to modify associations of specific infections or burden with dementia risk." (PMID 38248636, 2024). "Apolipoprotein E (apoE) epsilon variants and subtypes are also associated with dementia." (PMID 39678194, 2024). "Additionally, our study defined genetic risk for dementia using both APOE genotype and a comprehensive polygenic risk score." (PMID 39203912, 2024). "The risk of dementia was doubled for current smokers (HR = 1.97; 95% CI = 0.53, 7.32) and for individuals with diabetes (HR = 2.18; 95% CI = 1.14, 4.17) and tripled for carriers of the APOE ε4 allele (HR = 3.11; 95% CI = 1.92, 5.05)." (PMID 38865433, 2024).
dementia (continued). "The sensitivity analyses showed that the follow-up period and APOE ε4 status might have affected the findings between the retinal biomarkers and the risk of incident dementia." (PMID 39868381, 2024). "We found that APOE ε4 as genetic risk factor could exacerbate effect of sleep disorder on risk conversion to dementia." (PMID 38421124, 2024). "The first, and most straightforward (an individual‐level intervention), would be to facilitate neighborhood mobility for individuals already identified as high‐risk for dementia (e.g., because of APOE status, family history, a high risk‐index score, or early disease symptoms)." (PMID 38482967, 2024). "In this longitudinal study, we showed that APOE ε4 carriers in Aβ‐positive subjects were associated with a faster cognitive decline, independent of tau load, providing evidence that APOE ε4 with Aβ pathology exhibit an increased rate of dementia over time." (PMID 39014268, 2024). "Individuals with both Sleep+ and APOE+ had a higher risk of dementia compared to those with Sleep‐." (PMID 38421124, 2024). "In addition, APOE ε4 carrier status appeared to influence the association between nutrient status index and dementia incidence, with the association only evident in APOE ε4 carriers." (PMID 38865433, 2024). "In addition, all-cause dementia cases included a higher proportion of physically inactive participants (26.0% compared to 17.6%) and a much higher proportion of APOE ε4 carriers than controls (39.5% compared to 24.3%)." (PMID 38570813, 2024). "Analysis of 5,358 postmenopausal women from the Women’s Health Initiative Memory Study showed higher RC in individuals with Apolipoprotein E4 (apoE4) mutation, the most prevalent genetic risk factor of AD, was linked to increased dementia and cognitive impairment risk compared with lower RC group." (PMID 39323568, 2024). "This review will also cover genetic polymorphisms in the ApoE alleles leading to dyslipidemia induction that may regulate the pathways causing preE or dementia-like features in the reproductive age or later in life, respectively." (PMID 39857613, 2024). "Therefore, dementia risk attributed to apathy seems to be lower among APOE e4 carriers, potentially due to the greatest contribution of APOE e4-related pathways to the progression of neurodegeneration." (PMID 38473892, 2024). "Additionally, the apolipoprotein E (APOE) genotype has been identified as being significantly associated with the dementia risk." (PMID 39252463, 2024). "Age and APOE genotype were statistically significantly associated with all dementia outcomes." (PMID 38570813, 2024). "In addition, an interaction between the APOE e4 allele with both anxiety and depression was observed for conversion to dementia only in unadjusted analyses." (PMID 38473892, 2024). "When presented with three hypothetical dementia risk scenarios corresponding to different APOE genotypes, participants were more interested in genetic risk disclosure and more likely to participate in medication trials, when the presented likelihood of developing dementia was higher." (PMID 38167083, 2024). "We investigated whether any of the significant CpGs were also associated with dementia risk factors collected by the Framingham study, including APOE, diabetes, hypertension, years of education, BMI, and smoking." (PMID 39649611, 2024). "Patients carrying the APOE ε4 allele had a higher prevalence of dementia." (PMID 38792885, 2024). "APOE ε4 may increase risk for AD via its associations with environmental and behavioral factors that confer risk for dementia, such as stress exposure, sedentary lifestyle, trauma exposure, and TBI." (PMID 38951900, 2024). "Although ω-3 treatment failed to reach significant reduction in WML progression and neuronal integrity breakdown among all participants at risk for dementia, the findings suggest that APOE*E4 carriers may benefit from ω-3 treatment." (PMID 39088212, 2024).